THAP9 (THAP domain containing 9)
Description:
Active transposase that specifically recognizes the bipartite 5'-TXXGGGX(A/T)-3' consensus motif and mediates transposition.
Synonyms: hTh9; FLJ34093
Tractability: PROTAC: ubiquitination databases record sites on it.
Gene: Protein-coding gene on chromosome 4 (82,900,684 to 82,919,969, forward strand). Ensembl gene ENSG00000168152.
Subcellular location (Human Protein Atlas): Mitochondria
Gene Ontology:
Molecular function: protein binding; sequence-specific DNA binding; transposase activity; DNA binding
Biological process: DNA integration; DNA recombination; DNA transposition
Genetic constraint (gnomAD): Loss-of-function variants: 31 observed, 52.92 expected, observed/expected ratio (o/e) 0.59, 90% interval 0.44 to 0.79. The upper end of that interval is the gene's LOEUF score, 0.79, which puts it in group 3 of 6, group 1 being the genes least tolerant of losing a copy. Missense variants: 867 observed, 1,101.4 expected, observed/expected ratio (o/e) 0.79, 90% interval 0.74 to 0.83. Synonymous variants: 334 observed, 392.5 expected, observed/expected ratio (o/e) 0.85, 90% interval 0.78 to 0.93.
Homologues: Orthologues: chimpanzee THAP9 (99% identical), macaque THAP9 (98% identical), dog THAP9 (91% identical), pig THAP9 (85% identical), rabbit THAP9 (81% identical), guinea pig THAP9 (81% identical), tropical clawed frog thap9 (15% identical).
Diseases named in the same sentence as THAP9 in open-access papers:
THAP9 is named in the same sentence as 11 diseases in open-access papers, as found by Europe PMC text mining. Sharing a sentence is not in itself a finding about the gene and the disease. The quoted sentences say what the papers report.
Alzheimer disease (1 paper, 2022). A progressive, neurodegenerative disease characterized by loss of function and death of nerve cells in several areas of the brain leading to loss of cognitive function such as memory and language. "KEGG pathway analysis of genes co-expressed with THAP9 and THAP9-AS1 demonstrated the enrichment of pathways related to Herpes simplex virus 1 infection as well as several neurodegenerative disorders like Alzheimer’s disease, Parkinson’s disease, and Huntington’s disease." (PMID 35893234, 2022).
B-cell Lymphoma (1 paper, 2022). "Moreover, for the THAP9 gene, “mutation” appeared as the only form of alteration in all patients with colorectal cancer, mature B-cell Lymphoma, and head and neck Cancer." (PMID 35893234, 2022).
embryonal tumor (1 paper, 2022). "Notably, both THAP9 and THAP9-AS1 genes underwent amplification in breast cancer, non-small cell lung cancer, melanoma, embryonal tumor, and bone cancer but underwent “deep deletion” (indicates a deep loss, possibly a homozygous deletion) in uterine endometrioid carcinoma patients." (PMID 35893234, 2022).
cancer (1 paper, 2022). A tumor composed of atypical neoplastic, often pleomorphic cells that invade other tissues. "The expression levels of LIAS had a positive correlation with the expression levels of CTD-2366F13.1 (R = 0.47, p < 0.001), RAD17 (R = 0.48, p < 0.001), OCIAD1 (R = 0.49, p < 0.001), PACRGL (R = 0.49, p < 0.001), MRPS27 (R = 0.49, p < 0.001), and THAP9 (R = 0.49, p < 0.001) in pan-cancer." (PMID 35982953, 2022).
neurological disorders (1 paper, 2022). "It will be interesting to investigate the possible role of THAP9 in neurological disorders." (PMID 35893234, 2022).
THAP9 also shares sentences with these, for which no sentence is quoted: colorectal cancer (1 paper); head and neck cancer (1); medulloblastoma (1); melanoma (1); non-small cell lung carcinoma (1); Parkinson disease (1).